PXN (paxillin)
Diseases named in the same sentence as PXN in open-access papers (continued):
Sharing a sentence is not in itself a finding about the gene and the disease.
cancer (163 papers, 2008 to 2026). A tumor composed of atypical neoplastic, often pleomorphic cells that invade other tissues. "Alterations in the expression levels, localization, or phosphorylation status of paxillin are frequently linked to the metastasis of cancer cells." (PMID 40861820, 2025). "PXN is a focal adhesion protein widely implicated in the growth and metastasis of various types of cancer." (PMID 41148856, 2025). "Previous studies have reported that paxillin tyrosine phosphorylation is linked to cancer metastasis." (PMID 37958964, 2023). "FAK and Paxillin are two important components of focal adhesion and are closely linked to cancer metastasis." (PMID 35978854, 2022). "We found that differentially expressed PXN was mainly associated with regulation of the actin cytoskeleton, focal adhesions, pathways in cancer, and the PI3K-AKT signaling pathway." (PMID 34135128, 2021). "Regardless, aberrant expression levels of PXN were associated with poor prognoses in many types of cancer, which strongly indicates that PXN is a potential prognostic biomarker in patients with cancer." (PMID 34135128, 2021). "In this study, we investigated the pan-cancer analysis of PXN in various cancers and explored the association of its aberrant expression with patient survival outcomes." (PMID 34135128, 2021). "To study the relevance of the PXN gene mutation across various human cancers, we used the cBioPortal tool to detect PXN mutations in data extracted from TCGA dataset." (PMID 34135128, 2021). "Elevated paxillin phosphorylation is common in cancer tissues and is associated with tumorigenesis, EMT, and metastasis." (PMID 32814766, 2020). "Numerous abnormally large FAs accumulate in autophagy-deficient cancer cells, reflecting a role for autophagy in FA disassembly through targeted degradation of paxillin." (PMID 32401768, 2020). "LDE225 treatment can repress phosphorylation of focal adhesion kinase (FAK) and paxillin, two molecules critically implicated in integrin-dependent motility and invasiveness in numerous cancers, including MB." (PMID 31835472, 2019). "With PXN being a downstream target of several activated hormones and growth factors, it associates with aggressive cancers and reduces the survival rate of patients." (PMID 31269666, 2019). "As a consequence, we found cancer stem cell-associated proteins, such as mmp2, mmp9, mmp13, mmp14, paxillin, Ras, src and c-myc, as well as genes expressed in the immune system, such as C5, C9, and HMGB1." (PMID 31832023, 2019). "Paxillin is an interesting cancer metastasis target as point mutations and upregulation of paxillin are associated with poor cancer clinical outcomes." (PMID 31391572, 2019). "LRP-1 was shown to decrease talin levels and distribution in cancer cells and is required for paxillin and FAK association within focal adhesions." (PMID 29108253, 2017). "Paxillin is highly expressed in many cancers and is tightly associated with the development, progression, invasion, metastasis, and poor prognosis of multiple cancers." (PMID 28423510, 2017). "Mutations in paxillin, some that were observed to be associated with cancer were positioned in the intrinsically disordered regions between the LD motifs and not on the motifs themselves." (PMID 26928467, 2016). "Src kinase closely regulates the phosphorylation and activation of Cas adhesion protein and paxillin cytoskeletal protein, which operate cell migration in invasive cells during the development and pathological conditions associated cancer metastasis." (PMID 26945908, 2016). "This phenomenon suggests how cancer associated mutations in paxillin affect its interactions with Focal Adhesion Kinase (FAK)." (PMID 26928467, 2016). "The finding that pax−/− and paxN cells have an increased propensity to form CDRs was particularly intriguing in this regard, as it has been proposed that CDRs are related to invasive protrusions, and paxillin has been implicated in cancer progression." (PMID 22194823, 2011).
cancer (continued). "The expression level of PXN is linked to cancer drug resistance." (PMID 40821990, 2025). "Aberrant paxillin expression is associated with the malignant progression of cancer, so the modulation of paxillin expression may serve as a potential therapeutic target." (PMID 37175948, 2023). "We also took into account the fact that several cancer-linked Paxillin mutations have been mapped to the intrinsically disordered regions between LDs and not on the motifs themselves, such as P30S, G105A and A127T that lie between LD1 and LD2 and P233L and T255I that lie between LD3 and LD4." (PMID 33413438, 2021). "In a state of cancer caused by mutations in paxillin, the LD interactions could be hindered, as mutations in the unstructured segments result in abnormal binding of FAK to either of the LD motifs." (PMID 26928467, 2016). "While the effects of paxillin mutation on cell migration have been studied in 2D, little is known about its role in invasion through 3D ECMs, which is likely more physiologically relevant for development, wound healing, and cancer metastasis." (PMID 22194823, 2011). "Importantly, genes associated with cancer progression (i.e., Itgb2, Itgb5, paxillin, fyn) displayed increased expression, whereas those thought to suppress progression (i.e., vinculin, gravin) exhibited decreased levels of expression compared to MOSE-E cells." (PMID 21390237, 2011). "Interestingly, downregulation of RSPO4 in cell lines induced a strong inhibition of activated forms of the focal adhesion-associated proteins including Fak, Paxillin, and Src which are major signaling molecules involved in the regulation cancer cell stiffness and cell locomotion/migration." (PMID 36611933, 2022). "Due to both FAK and paxillin upregulation in cancer, inhibition of the FAK-paxillin PPI is a promising therapeutic approach." (PMID 41492449, 2026). "Others have reported that in fibroblasts or epithelial-like cancer cells, paxillin’s nuclear localization is regulated by serine phosphorylation of its nuclear export LD motif and/or nuclear-localizing LIM domain." (PMID 40926123, 2025). "In summary, we report a feasible strategy to target elusive PPIs and its specific application to the design of effective therapeutics targeting the FAK-paxillin interaction, central to multiple hallmarks of cancer." (PMID 40021642, 2025). "It has been reported that paxillin also localizes in the nucleus to directly exert its transcription activity in cancer cells." (PMID 39991922, 2025). "CDC42 has been documented to accelerate cancer development through the activation of the integrin β1/FAK/paxillin signal transduction pathway." (PMID 40861820, 2025). "Research has particularly demonstrated a strong link between high paxillin expression and more aggressive forms of cancers, including those of the breast, colon, and lung, with this overexpression tied to a poorer prognosis." (PMID 40001476, 2025). "The FAK scaffold function largely involves the interaction between FAK’s focal adhesion targeting (FAT) domain and paxillin, ultimately regulating many hallmarks of cancer." (PMID 40021642, 2025). "For instance, paxillin enhances endothelial cell adhesion and expansion during angiogenesis, while kindlin-2 promotes cancer cell invasion through integrin β1 activation." (PMID 40001476, 2025). "Together, HLF loss decreases LPXN expression, enhancing the integration of collagen stiffness and the actin cytoskeleton through paxillin, ultimately promoting cancer cell migration." (PMID 40473600, 2025). "Understanding these mechanisms in detail is crucial, as they provide a foundation for therapeutic interventions targeting paxillin and kindlin in diseases like cancer and tissue degeneration." (PMID 40001476, 2025). "Mechanistically, HLF regulates LPXN expression, modulating the integration of collagen’s mechanical cues with the actin cytoskeleton through Paxillin, thereby suppressing cancer cell migration and lung metastasis." (PMID 40473600, 2025).
cancer (continued). "Targeted therapies for paxillin and kindlin focus on inhibiting or reversing these functions to mitigate cancer progression and improve patient outcomes." (PMID 40001476, 2025). "The analysis of post irradiated samples, exhibited for cancer cells the existence of a significant dose-dependent increase in cytoplasmic paxillin expression, reflecting elevated paxillin levels at FAs sites." (PMID 38903185, 2024). "We further elucidated that high PD-L1 expression in cancer cells resulted from enhanced phosphorylation of the Paxillin (PXN)/AKT signaling pathway triggered by CXCL5 stimulation of CXCR2 in a dose-dependent manner." (PMID 39034411, 2024). "Background and objective: The complex focal adhesion kinase (FAK)/Src and paxillin seem to play a key role in the pathogenesis and progression of cancer." (PMID 39036223, 2024). "While a few studies have identified paxillin as a novel interactor of PTEN, the mechanisms underlying the upregulation of paxillin and the significance of its coordination with PTEN in cancer progression are just beginning to be revealed." (PMID 37853467, 2023). "In fibroblasts and cancer cells, paxillin localizes to nascent adhesions at the leading edges of migrating cells." (PMID 37250402, 2023). "Though the detection of paxillin expression and the development of new oncology drugs targeting the paxillin gene are promising prospects for cancer clinical prognosis and treatment, many unanswered questions arise." (PMID 37175948, 2023). "As paxillin expression is more widely studied in cancer, the clinical significance of paxillin has received increased amounts of attention." (PMID 37175948, 2023). "Various studies have demonstrated that PXN enhances cancer proliferation through the activation of multiple signaling pathways." (PMID 36923874, 2023). "We found that cancer cells located close to nerves (within 200 μm diameter) expressed more p-paxillin (15.57% of total tissue area) than cancer cells located in the pancreas distant from nerves (4.23% of total tissue area)." (PMID 37607005, 2023). "Paxillin is a scaffold protein that regulates actin cytoskeleton dynamics and thereby cell adhesion and the migration of cancer cells." (PMID 37686651, 2023). "Norcantharidin disrupts F-actin reorganization by inhibiting the FAK/paxillin axis, which inhibits cancer cell invasion." (PMID 37175948, 2023). "Src family tyrosine kinases phosphorylate paxillin and a broad-spectrum Src family tyrosine kinase inhibitor is currently used in the clinic to treat cancer." (PMID 37958964, 2023). "LncRNA XIST, miR-137, and paxillin can form a ceRNA network to promote the proliferation and invasion of cancer cells." (PMID 37175948, 2023). "Some kinases and regulatory proteins can promote the phosphorylation of paxillin to elevate cancer cell invasion." (PMID 37175948, 2023). "Paxillin-mediated ERK activation using the phosphorylating Bcl-2 protein to increase its stability was shown to be responsible for paxillin-mediated cancer cell invasiveness." (PMID 37175948, 2023). "All in all, further exploration of the paxillin pathway will help towards finding a solution to cancer metastasis and chemoresistance in the future." (PMID 37175948, 2023). "In this sense, several authors have reported that paxillin, α-adducin, α-parvin, and cadherin-11 are altered in various types of cancer, including BC." (PMID 37686651, 2023). "Elevated levels of paxillin expression have been observed in various cancer types, with tyrosine phosphorylation shown to play a critical role in driving cancer cell migration." (PMID 37958964, 2023). "Despite the fact that the role of paxillin in cancer has been studied for many years, many studies have also demonstrated its value as a prognostic factor in cancer patients, and this topic remains controversial." (PMID 37175948, 2023). "Specifically, paxillin Tyr31 and Tyr118 phosphorylation induced by activated integrins have been shown to promote the migration of cancer cells." (PMID 37958964, 2023).
cancer (continued). "Currently, certain drugs to treat cancer work by targeting paxillin or signaling pathways involving paxillin." (PMID 37175948, 2023). "Here, we will briefly discuss cancer therapeutics and potential drugs targeting paxillin as well as its signaling pathways." (PMID 37175948, 2023). "Mechanistically, cancer-cell-derived TGF-α upregulated CCL2 secretion from sensory neurons, which induced hyperphosphorylation of the cytoskeletal protein paxillin via CCR4 on cancer cells." (PMID 37607005, 2023). "To test if MAP4K4 is regulating focal adhesions disassembly in A431 carcinoma cells, we performed live imaging of the focal adhesion component paxillin fused to GFP." (PMID 37369604, 2023). "Paxillin (PXN), a key component of the focal adhesion complex, is associated with cancer progression." (PMID 35330327, 2022). "Epithelial-to-mesenchymal transition (EMT) and motility of cancer cells are associated with transendothelial migration, and these processes are regulated by the PI3K/AKT and FAK/Paxillin pathways." (PMID 36160416, 2022). "Secreted TSP1 from cancer cells with Rab37 exocytic function inhibits the p-focal adhesion kinase (p-FAK)/p-paxillin/p-ERK migration signaling in both cancer epithelial cells and their surrounding endothelial cells." (PMID 35927755, 2022). "The P130cas adaptor protein, also known as BCAR1, is one of the Src substrates co-localizes with paxillin in FAs and is involved in cell migration, survival, transformation, invasion, and cancer." (PMID 36088346, 2022). "Analysis of the cancer genome atlas (TCGA) database showed that expression of PXN significantly predicted a worse prognosis (5-year overall survival rate; p = 0.0283)." (PMID 34946859, 2021). "In conclusion, the results of this pan-cancer analysis indicated that aberrant expression of PXN correlates with poor prognosis, immune cell infiltration, and protein phosphorylation in different cancer types." (PMID 34135128, 2021). "Functional assays in HNSCC cells showed that knockdown of PXN expression attenuated cancer cell migration and invasion, suggesting that aberrant expression of PXN contributed to HNSCC cell aggressiveness." (PMID 34946859, 2021). "In this study, we identified the relationship of the PXN gene in multiple cancer tumorigenesis models via a pan-cancer analysis of TCGA, CPTAC, HPA cohort, and GEO databases." (PMID 34135128, 2021). "Next, we studied the correlation between expression level of the PXN gene and cancer prognoses by using the Kaplan-Meier plotter." (PMID 34135128, 2021). "PXN expression had functions associated with CD8+ T-cell infiltration, cancer-associated fibroblasts, and endothelial cells in different tumors." (PMID 34135128, 2021). "PXN knockdown significantly inhibited migration and invasion of cancer cell lines by interfering with the epithelial-mesenchymal transition process." (PMID 34135128, 2021). "It has been reported that control of focal adhesion proteins such as paxillin is important for cancer metastasis, which depends on cellular migration and cell-matrix adhesion." (PMID 34112111, 2021). "Paxillin is a FA adapter protein that plays distinct roles in the regulation of cell movement, cancer development, and metastasis." (PMID 34654797, 2021). "Previous studies showed that aberrant expression of PXN was detected in a wide range of cancers, and its overexpression was usually correlated with worse prognosis of the patients." (PMID 34946859, 2021). "Recent reports have shown that several dysregulated non-coding RNAs (long non-coding RNAs [lncRNAs] and miRNAs) are involved in aberrant expression of PXN in cancer cells." (PMID 34946859, 2021). "According to the Oncomine dataset, TCGA dataset, and Kaplan-Meier plotter, the gene expression analysis suggests that abnormal expression of PXN occurred frequently in various types of cancer." (PMID 34135128, 2021).
cancer (continued). "Meanwhile, many studies have reported that aberrant PXN expression is often found in relation to the initiation, progression, or metastasis of human cancer." (PMID 34135128, 2021). "We also observed a correlation between PXN expression level and the pathological stages of cancers, including in BRCA and LIHC (P < 0.01) via the “Pathological Stage Plot” module of GEPIA2." (PMID 34135128, 2021). "Analysis of the epigenetic modification that regulates PXN expression is required for each cancer type." (PMID 34946859, 2021). "We found eight MAPK pathway genes (including MYC, WNK1 and PXN) that are classifiable as “common essential” (see the “Methods” section) among all cancer cell lines." (PMID 33398072, 2021). "We also used the HPA cohort to investigate PXN protein expression levels in various types of cancer." (PMID 34135128, 2021). "Many non-coding RNA molecules are involved in the regulation of PXN expression, and the complexity of the molecular mechanisms of cancer cells has been clarified." (PMID 34946859, 2021). "We analyzed PXN expression, immune cell infiltration, prognosis, and biological function across different types of tumors included in The Cancer Genome Atlas and Gene Expression Omnibus datasets." (PMID 34135128, 2021). "We used the CPTAC dataset to investigate the function and localization of the PXN protein in various cancers." (PMID 34135128, 2021). "Aberrant expression of PXN facilitated cancer cell migration and invasion, and its expression was closely associated with HNSCC molecular pathogenesis." (PMID 34946859, 2021). "It has been reported that several miRNAs (e.g., miR-132, miR-137, miR-145, miR-212, and miR-218) directly control PXN expression in cancer cells." (PMID 33322675, 2020). "Our findings on the inhibitory effects of ropivacaine on Rac1 activity is consistent with the previous report that ropivacaine inhibits Rac1/JNK/paxillin in cancer cells." (PMID 32450791, 2020). "The pathways activated by PXN enhance cancer cell malignant progression and metastasis in a wide range of cancers." (PMID 33322675, 2020). "The role of vimentin and phospho-paxillin as active players in cell focal adhesion and migration, as well as in pathological conditions, including cancer development and metastasis, is widely discussed in literature." (PMID 32664186, 2020). "PXN knockdown significantly inhibited cancer cell migration and invasion, possibly by regulating epithelial–mesenchymal transition." (PMID 33322675, 2020). "Because integrins, paxillin, thrombospondin, laminins, and collagens are positioned upstream of multiple signaling cascades which contribute to cancer invasion and metastasis, these represent desired targets to inhibit these pathways." (PMID 32670895, 2020). "This supports our finding that increased pFAK, active integrin, and paxillin, induced by depletion of RITA in diverse cancer cell lines and MEFs, disrupt FA dynamics and cause its delayed turnover resulting in reduced migration." (PMID 31353815, 2019). "The correlation between cancer migration and actin cytoskeleton assembly was consistent with the ability of F806 to prevent the aggregation of Paxillin, an essential protein for focal adhesion formation through binding to the ends of actin filaments." (PMID 30327774, 2018). "Our data collectively suggest that AZD0530 reverses the LIF-associated cancer invasive phenotype, at least partly, by increasing cytoplasmic YAP1 and suppressing expression of the focal adhesion components p-PXN and p-FAK." (PMID 30504771, 2018). "In the recent past, the role of FAK, Paxillin, and Moesin in relationship with sex steroids in the biology of normal and cancer cells has been the subject of extensive investigation." (PMID 30013514, 2018). "In the current study, we investigated the mechanisms underlying the LIF-mediated cancer metastasis and provide evidence linking LIF with cancer dissemination by driving invadopodia formation and modulation of the YAP1-FAK/PXN pathway." (PMID 30504771, 2018).